WWC3 (WWC family member 3)
Description:
Regulator of the Hippo signaling pathway, also known as the Salvador-Warts-Hippo (SWH) pathway. Enhances phosphorylation of LATS1 and YAP1 and negatively regulates cell proliferation and organ growth due to a suppression of the transcriptional activity of YAP1, the major effector of the Hippo pathway.
Synonyms: KIAA1280; BM042
Tractability: PROTAC: ubiquitination databases record sites on it.
Gene: Protein-coding gene on chromosome X (10,015,254 to 10,144,474, forward strand). Ensembl gene ENSG00000047644.
Subcellular location: Cytoplasm, cytosol
Subcellular location (Human Protein Atlas): Cytosol; Actin filaments
Gene Ontology:
Molecular function: kinase binding; molecular adaptor activity; signaling adaptor activity
Biological process: hippo signaling; negative regulation of cell population proliferation; negative regulation of hippo signaling; negative regulation of organ growth; negative regulation of transcription by RNA polymerase II; cell migration; regulation of DNA-templated transcription; regulation of hippo signaling
Cellular component: cytoplasm; cytosol
Homologues: Orthologues: macaque WWC3 (98% identical), chimpanzee WWC3 (97% identical), dog WWC3 (86% identical), rat Wwc3 (85% identical), guinea pig WWC3 (78% identical), pig WWC3 (77% identical), tropical clawed frog wwc3 (70% identical), zebrafish wwc3 (55% identical), Drosophila melanogaster kibra (30% identical). Paralogues in human: WWC2 (44% identical), WWC1 (40% identical).
Diseases named in the same sentence as WWC3 in open-access papers:
WWC3 is named in the same sentence as 15 diseases in open-access papers, as found by Europe PMC text mining. Sharing a sentence is not in itself a finding about the gene and the disease. The quoted sentences say what the papers report.
lung carcinoma (8 papers, 2019 to 2022). "WBP2 acts as a competitive inhibitor by binding to the WW domain of WWC3 protein in lung carcinoma cells to limit WWC3–LATS1 association." (PMID 34831354, 2021). "Furthermore, WBP2 has been recently shown to associate with LATS2 and WWC3 to inhibit the Hippo tumor suppressor pathway in gastric and lung cancers, in turn limiting cancer proliferation and invasion." (PMID 34197030, 2022). "In lung cancer cells, all three PY motifs of WBP2 are required for association with the WW domain of WWC3." (PMID 34831354, 2021). "Some studies have reported that WWC3 inhibits the epithelial‒mesenchymal transition of lung cancer by activating the Hippo‐YAP signalling pathway." (PMID 32892482, 2020). "Lower expression of protein WWC3 was reported in lung cancer cells." (PMID 35454982, 2022). "Knockdown of WWC3 enhanced the epithelial–mesenchymal transition of lung cancer cells." (PMID 35454982, 2022). "Furthermore, confocal laser scanning revealed a co-localization of WBP2 and WWC3 in the cytosol of lung carcinoma cells." (PMID 34831354, 2021). "Recent studies have demonstrated that WWC3 regulates the Wnt and Hippo pathways via Dvl protein and LATS1 to inhibit the invasion and metastasis of lung cancer cells." (PMID 32892482, 2020).
glioma (3 papers, 2019 to 2021). A benign or malignant brain and spinal cord tumor that arises from glial cells (astrocytes, oligodendrocytes, ependymal cells). "In contrast, a low WWC3 level forces an increase in Wnt signaling and subsequent proliferation, migration and invasion of glioma cells." (PMID 33467643, 2021). "miR-10b-5p, highly expressed in glioma, inhibits the tumor-suppressive function of WWC3, thus promoting low Hippo pathway activity and enhanced glioma malignancy." (PMID 33467643, 2021). "Although the expression of WWC3 is known to be downregulated in human glioma tissues and cells, the mechanism through which WWC3 affects glioma cell behaviour remains to be fully elucidated." (PMID 32892482, 2020). "U87 and U251 glioma cells that overexpressed miR‐10b‐5p, WWC3 or WWC3 (non‐3′‐UTR) were constructed." (PMID 32892482, 2020). "The results showed that the protein levels of WWC3 were low in different glioma tissues, progressively reduced with increasing grade and downregulated in U87 and U251 glioma cells." (PMID 32892482, 2020). "The WWC3 knockdown promoted the cell viability, migration and invasion of U87 and U251 glioma cells, but suppressed cell apoptosis." (PMID 32892482, 2020). "Subsequently, the p‐YAP levels in the U87 and U251 glioma cells were detected using western blotting after the overexpression or knockdown of WWC3." (PMID 32892482, 2020). "To further validate the function of miR‐10b‐5p on WWC3, we assessed the effect of miR‐10b‐5p and WWC3 on the malignant biological behaviour of glioma cells." (PMID 32892482, 2020). "Compared with miR‐10b‐5p‐NC+WWC3‐NC, the cell viability, migration and invasion abilities of U87 and U251 glioma cells were found to be significantly enhanced in the miR‐10b‐5p+WWC3‐NC group, but with attenuated cell apoptosis." (PMID 32892482, 2020). "TSLNC8 serves as a competitive endogenous RNA, attenuating the miR‐10b‐5p inhibitory effect on WWC3, thereby inhibiting the viability, migration and invasion of glioma cells and promoting glioma cell apoptosis." (PMID 32892482, 2020). "As a key upstream signalling molecule of the Hippo signalling pathway, WWC3 activated this signalling pathway and inhibited the malignancy of glioma cells." (PMID 32892482, 2020). "WWC3 overexpression was found to exert a significant inhibitory effect on the cell viability, migration and invasion of U87 and U251 glioma cells, but promoted cell apoptosis." (PMID 32892482, 2020). "Compared with the miR‐10b‐5p+WWC3‐NC group, the results of miR‐10b‐5p+WWC3 group showed that WWC3 reversed the promotion mediated by miR‐10b‐5p overexpression on glioma cell malignant biological behaviour." (PMID 32892482, 2020). "Hence, WWC3-mediated inhibition of Wnt signaling results in decreased glioma cell proliferation and migration." (PMID 33467643, 2021). "Our results indicate that the BACH2 and FUS/TSLNC8/miR‐10b‐5p/WWC3 axis is responsible for glioma development and could serve as a potential target for the development of new glioma therapies." (PMID 32892482, 2020). "Furthermore, the function of WWC3 on the malignant biological behaviour of glioma cells was assessed." (PMID 32892482, 2020). "BACH2 and FUS/TSLNC8/miR‐10b‐5p/WWC3 axis is responsible for glioma development and could serve as a potential target for glioma therapies." (PMID 32892482, 2020). "The expression of WWC3 is downregulated in human glioma tissues and cells." (PMID 32892482, 2020). "In this study, the overexpression of WWC3 significantly restrained the viability, migration and invasion of glioma cells and promoted glioma cell apoptosis, while the knockdown of WWC3 had the opposite effect, suggesting that WWC3 acts as a tumour suppressor in glioma cells." (PMID 32892482, 2020). "This was found to reduce WWC3 expression by enhancing the binding of miR‐10b‐5p to the WWC3 3′‐UTR region, blocking the Hippo signalling pathway and promoting the malignancy of glioma cells." (PMID 32892482, 2020).
glioma (continued). "Taken together, these results indicate that BACH2 and FUS interaction enhanced the inhibition of the protein levels of WWC3 and YAP phosphorylation, TSLNC8 promoted the protein levels of WWC3 and YAP phosphorylation via miR‐10b‐5p and affected the malignant biological behaviour of glioma cells." (PMID 32892482, 2020).
breast carcinoma (2 papers, 2018 to 2026). "Furthermore, MAGEE1 is frequently mutated and considered a candidate cancer gene in breast cancer, WWC3 has a high potential for complete or partial escape in ovarian cancer, and HUWE1 is known as a tumor suppressor gene." (PMID 41522471, 2026). "Accordingly, the correlation between expression of WWC2/WWC3 and clinical features of breast cancer must be further determined." (PMID 30042827, 2018).
Non-Small Cell carcinoma (2 papers, 2021 to 2022). "Within the presence of WWC3, the activity of caspase-3 and caspase-7 increases and WWC3 proteins act as an autophagy regulator in Non-Small Cell carcinoma." (PMID 35933451, 2022).
colorectal carcinoma (1 paper, 2024). A malignant epithelial neoplasm that arises from the colon or rectum and invades through the muscularis mucosa into the submucosa. "In colorectal carcinoma (CRC), Chen Li proved the inhibition effect of lncRNA NBAT-1 on the development of OXA-resistant CRC cells by suppressing miR-4504 to mediate the WWC3/LATS1/YAP axis." (PMID 38243168, 2024).
diabetes (1 paper, 2022). "Downregulation of WWC3 in diabetic groups might indicate the aggressive nature of EC in the presence of diabetes." (PMID 35454982, 2022). "Differential expression of proteins linked to cancer metastasis, such as the upregulation of vinculin and endoplasmin and downregulation of WWC3 and IFT88, was seen in the patients with diabetes." (PMID 35454982, 2022). "In addition, protein changes associated with cancer metastasis, such as the upregulation of vinculin and endoplasmin, and downregulation of WWC3 and IFT88, were seen in the patients with diabetes." (PMID 35454982, 2022).
gastric cancer (1 paper, 2020). A primary or metastatic malignant neoplasm involving the stomach. "The downregulation of WWC3 is associated with the inhibition of Hippo signalling and results in a poor prognosis of human gastric cancer." (PMID 32892482, 2020).
pulmonary fibrosis (1 paper, 2025). Chronic progressive interstitial lung disorder characterized by the replacement of the lung tissue by connective tissue, leading to progressive dyspnea, respiratory failure, or right heart failure. "Pulmonary fibrosis showed increased expression of serine/threonine-protein kinase PLK2 (Q9NYY3) and NEDD4-binding protein 2 (Q86UW6), while alveolar infiltrates exhibited reduced expression of protein WWC3 (Q9ULE0), Rho-associated protein kinase 1 (Q13464), and apolipoprotein A-IV (P06727)." (PMID 41279897, 2025).
tumor (13 papers, 2019 to 2026). "The tumor volume change rate following SSA treatment was correlated with the expression levels of WWC family member 3 (WWC3) and serine incorporator 1 (SERINC1) and tended to correlate with zinc finger AN1-type containing 3 (ZFAND3) expression." (PMID 36435867, 2022). "WWC3 is a tumor suppressor that is downregulated in cancer and low WWC3 expression is associated with poor prognosis of cancer patients." (PMID 33466455, 2021). "In recent years, the regulation of WWC3 in tumours has received a lot of attention." (PMID 32892482, 2020). "This review synthesizes current evidence demonstrating that WWC1, WWC2, and WWC3 exert context-dependent effects across malignancies, with WWC2 consistently functioning as a tumor suppressor while WWC1 and WWC3 display tissue-specific variability." (PMID 41727322, 2026). "ATP2A2 and ARID5B correlated with the GH change rate in the octreotide loading test, and WWC3, SERINC1, and ZFAND3 correlated with the tumor volume change rate after somatostatin analog treatment." (PMID 36435867, 2022). "ATP2A2 and ARID5B were identified as being correlated with the GH change rate in response to octreotide treatment, and WWC3, SERINC1, and ZFAND3 were identified as being correlated with the tumor volume change rate in response to SSA treatment." (PMID 36435867, 2022). "However, in NSCLC, WWC3 and FRMPD1 levels are reduced and Hippo signaling is low, which correlates with advanced tumor–node–metastasis stage, lymph node metastasis and poor prognosis." (PMID 33467643, 2021). "Certain assays of tumor suppression show a mutual requirement for PTPN14 and WWC1 (KIBRA), but potential contributions of WWC2 and WWC3 in the same assays have not been thoroughly tested." (PMID 38496413, 2024).
cancer (8 papers, 2018 to 2026). A tumor composed of atypical neoplastic, often pleomorphic cells that invade other tissues. "Interestingly, studies in Tasmanian devils showed that loss-of-function mutations in WWC3 are linked to a transmissible cancer of Schwann cell origin." (PMID 33467643, 2021). "This unique cancer type in the Tasmanian devil presents specific genomic alterations which can also be found in human SCHW and neurofibromas, pointing to a putative (NF2-dependent) role of WWC3 in these types of human cancer." (PMID 33467643, 2021). "This review has been designed to provide an update on the published data linking WWC1, WWC2 and WWC3 to cancer, with a focus on Hippo pathway-dependent mechanisms." (PMID 33467643, 2021). "Considering the structural similarities and putative redundant functions of all three WWC protein family members, WWC2 and WWC3 are supposed to play a WWC1-comparable role in human cancer." (PMID 33467643, 2021).
neurodegenerative disease (1 paper, 2021). A disorder of the central nervous system characterized by gradual and progressive loss of neural tissue and neurologic function. "In addition, differentially expressed genes in B cells were identified; both the upregulated genes (KIR3DL2, QPCT, PPP2R2B) and the downregulated genes (FRAT2, WWC3, SPG20) had certain connections with neurodegenerative diseases." (PMID 34880454, 2021). "In B cells, the upregulated genes KIR3DL2, QPCT, and PPP2R2B are all involved in neural function and neurodegenerative diseases, and the downregulated genes FRAT2 and WWC3 are involved in the Wnt/β-Catenin signaling pathway, which is associated with AD pathogenesis." (PMID 34880454, 2021).
WWC3 also shares sentences with these, for which no sentence is quoted: atherosclerosis (1 paper); neurodevelopmental disorder (1); ovarian carcinoma (1); respiratory diseases (1).